SORT1 (sortilin 1)
Diseases named in the same sentence as SORT1 in open-access papers (continued):
Sharing a sentence is not in itself a finding about the gene and the disease.
cancer (28 papers, 2013 to 2025). A tumor composed of atypical neoplastic, often pleomorphic cells that invade other tissues. "SORT1 was linked to oncogenesis and associated with poor prognosis, has been reported in most human cancers." (PMID 40750784, 2025). "The effects of TH1902 on both the overall cancer cell compartment and the more specific CSC niche positions this PDC among the promising therapeutic strategies to impact the development of human SORT1+ cancers and to reduce the risk of recurrence." (PMID 36145658, 2022). "In addition, the expression of SORT1 is reported to be altered in various types of cancer, and its dysregulation is often associated with tumour progression and metastasis." (PMID 38255751, 2024). "Deregulation in SORT1 functions has been implicated in cardiovascular disease, Alzheimer’s disease, and diabetes, whereas its upregulation has been documented in several forms of cancer." (PMID 36145658, 2022). "Furthermore, SORT1 is overexpressed in cancer tissues and has been implicated in promoting cancer cell proliferation and survival, thus making it a promising therapeutic target for various cancers, including breast and ovarian cancers." (PMID 39209807, 2024). "The pathogenetic role of SORT1 in various cancers, including breast, colorectal, and gastric malignancies, has been investigated; however, its role in NSCLC remains largely unexplored." (PMID 40781926, 2025). "Angiogenesis plays a crucial role in cancer progression, and SORT1 has been reported to have a significant impact on cancer progression by regulating angiogenesis in several cancer types." (PMID 39209807, 2024). "The intricate involvement of SORT1 in signalling pathways related to tumour development suggests its potential as a biomarker for cancer prognosis and as a target for novel therapeutic strategies." (PMID 38255751, 2024). "H&E staining of resected tumors exhibited significantly enlarged SORT1-positive cancer cell morphology upon six cycles of treatment; this morphology was maintained off-treatment." (PMID 38482021, 2024). "Understanding of the SORT1-mediated molecular internalization mechanism and the in vivo impact of the peptide-docetaxel conjugate TH1902 on SORT1-positive cancers is steadily increasing." (PMID 38482021, 2024). "NT, NTR1, and SORT1 are mostly expressed in these three cancers, and their involvement in oncologic processes such as proliferation and invasion seems to match, as does their impact on prognosis for most." (PMID 39519199, 2024). "This exploration not only addresses cardiovascular health but also opens avenues for understanding the broader impact of these interventions on neurodegenerative diseases and cancer, offering a holistic perspective on SORT1-targeted therapeutics." (PMID 38255751, 2024). "In this study, we aimed to clarify the status of SORT1 mRNA expression in NSCLC, following our pilot observations, which demonstrated downregulation of SORT1 in this tumour type, contrasting the published data in other human cancers." (PMID 38893272, 2024). "Previous studies have indicated that SORT1 is overexpressed in cancer tissues and plays an oncogenic role in various cancers, including HCC." (PMID 39209807, 2024). "IHC analysis further revealed reduced Ki67 cell proliferation, accompanied by increased STING and CD45 staining, in TH1902-treated tumors and a sustained expression of SORT1 on cancer cells following treatments." (PMID 38482021, 2024). "Here, we exploited the in vivo targeting of SORT1-positive cancer cells to document its impact within the iTME." (PMID 38482021, 2024). "Nevertheless, the SORT1 gene appears to potentially act as an oncogene or as a tumour suppressor gene in different cancer types." (PMID 38893272, 2024). "This interaction enhances the delivery of the cytotoxic agent directly to SORT1-expressing cancer cells, improving the efficacy of the treatment while reducing off-target effects and systemic toxicity." (PMID 39033780, 2024).
cancer (continued). "On the other hand, SORT1 was upregulated in many types of human cancer, such as breast, ovarian, pancreatic, melanoma, and pituitary adenoma." (PMID 38139459, 2023). "The expression of SERPINA1 and SORT1 has previously been shown to be increased in several types of cancers; however, the two proteins served as two protective biomarkers in the current study." (PMID 36765702, 2023). "Recent evidence suggests that Sort1 promotes carcinogenesis and tumor progression in multiple types of cancers." (PMID 35847356, 2022). "At the same time, it was found by pan-cancer analysis that the Sort1 gene has high expression and low expression in all tumors." (PMID 35847356, 2022). "The results of immunohistochemistry further indicated that Sort1 was more expressed in the cancer tissues, especially in poorly differentiated tumors, compared with the paracancerous ones." (PMID 35847356, 2022). "Here, through IHC scoring and Western blotting, high expression of SORT1 was observed in ovarian and endometrial metastatic and malignant tumor tissues as well as of corresponding cancer cell lines, in comparison to the respective healthy tissue." (PMID 35454785, 2022). "It is also the first demonstration of SORT1 protein expression in cancer stem-like cell models that provides support to the SORT1 activity involved in the propagation of stem cells in several types of cancers." (PMID 36145658, 2022). "A link between altered SORT1 expression and cancer treatment has only been reported for B acute lymphoblastic leukaemia." (PMID 33325631, 2021). "Both miR‐146a and SORT1 play a role in influencing the phenotype of cancer cells." (PMID 40781926, 2025). "Collectively, these findings suggest that SORT1 misregulation is sensitive to human cancers and may represent a potential biomarker for clinical surveillance of tumor progression." (PMID 40750784, 2025). "However, the molecular mechanisms through which SORT1 impacts the phenotypic characteristics of NSCLC cancer cells are not yet fully understood." (PMID 40781926, 2025). "Notably, the overexpression of SORT1 has been observed in various tumors, including breast, ovarian, and thyroid cancers." (PMID 40781926, 2025). "SORT1’s involvement in diverse physiological processes positions it as a potential therapeutic target for a broader spectrum of diseases, including neurodegenerative conditions and various cancers." (PMID 38255751, 2024). "In some instances, SORT1 acts as a mediator of cellular processes that promote cancer growth, such as regulating cell survival pathways and influencing the invasive potential of cancer cells." (PMID 38255751, 2024). "Recently, screening of 19 cancer TMAs with 2800 evaluable cancer cores confirmed that SORT1 is highly expressed in multiple tumors and may therefore be a promising target for the delivery and internalization of anticancer therapeutic agents." (PMID 38482021, 2024). "Additionally, SORT1 also modulates the response to therapeutic interventions, impacting the efficacy of cancer treatments." (PMID 38255751, 2024). "Expanding the scope of relevance, these intricate molecular interactions within the SORT1–GRN network may also have implications in cancer biology." (PMID 38255751, 2024). "Therefore, understanding the SORT1–GRN network’s role in microcalcification provides insights that extend beyond cardiovascular diseases to potentially include aspects of cancer pathophysiology." (PMID 38255751, 2024). "Furthermore, the results of cellular function assay are consistent with recent studies, suggesting that the oncogenic role of PSMD14 and SORT1 in various cancer." (PMID 36959615, 2023). "Interestingly, the overexpression of sortilin (SORT1)/NTSR3 in prostatic, colonic, and pancreatic cancers showed that sortilin in association with NT is responsible for cancer cell growth." (PMID 37298595, 2023). "These suggest that SORT1-targeted ADCs may be a promising agent for SORT1-positve cancers in clinic." (PMID 38139459, 2023).
cancer (continued). "Thus, developing more specific and effective therapeutics is a prerequisite for significant improved outcomes in those cancer patients bearing SORT1-positive gynecological tumors." (PMID 35454785, 2022). "Increased levels of SORT1 expression have also been reported for other forms of cancers, and some studies have suggested that targeted inhibition of SORT1 expression and/or function could be useful for slowing the growth of tumors." (PMID 35454785, 2022). "This further supports SORT1-positive cancers as therapeutic targets." (PMID 35454785, 2022). "For example, SORT1 gene (sortilin 1) occupies a hub position between three functional metagroups that connect vesicle trafficking, tyrosine phosphorylation signalling and molecular processes usually altered in cancer." (PMID 27871224, 2016). "Therefore, while SORT1 mRNA may be elevated in cancer cells, the overall expression level in the cancer tissue could be reduced due to its lower expression in non‐cancerous cells within the tumor microenvironment." (PMID 40781926, 2025). "Similarly, in cancer, where interactions between the tumour microenvironment and immune cells are crucial, SORT1-mediated effects on monocyte behaviour could impact the tumour’s ability to manipulate its surroundings." (PMID 38255751, 2024). "Given the intricate involvement of SORT1 in multiple common pathways, evaluating the efficacy of empagliflozin, sitagliptin, and lycopene in mitigating neurodegenerative processes or influencing cancer progression could reveal unexpected therapeutic benefits." (PMID 38255751, 2024). "Therefore, we investigated if SORT1 could induce endocytosis of 8D302 into SORT1-positive cancer cells." (PMID 38139459, 2023). "Accordingly, we performed a retrospective clinical investigation of SORT1 expression, and the expression of SORT1 is significantly upregulated in HCC primary tumors compared with para-carcinoma tissue, which is correlated with poor prognosis of HCC patients." (PMID 40750784, 2025). "EMT is a critical mechanism in cancer metastasis, and we demonstrated the regulation of EMT-related proteins according to SORT1 expression status." (PMID 39209807, 2024). "Due to the vital role played by lysosomes in cancer, a LRRS signature was constructed, including 8 genes, namely, CLN3, GBA, CTSA, BSG, APLN, SORT1, ANXA2, and LAPTM4B." (PMID 38114725, 2023). "Altogether, these results suggest a certain correlation between Sort1 expression and immune cell infiltration, with the tumor microenvironment of HCC likely to be involved in allowing cancer cells to evade the immune system." (PMID 35847356, 2022). "Overall, current data evidence for the first time that 1) SORT1 itself exerts a crucial role in both ES-2 and MDA-MB-231 VM, and that 2) VM in these cancer cell models can be efficiently inhibited by the peptide-drug conjugates TH1902/TH1904." (PMID 34751242, 2021). "The expression of NOX4 and SORT1 were also significantly increased in aggressive cancer tissue when compared with non-malignant (P ≤ 0.01) and indolent cancer tissue (P ≤ 0.05)." (PMID 26473288, 2015). "Therefore, SORT1-targeted ADCs may be more effective than HER2-targeted ADCs for the treatment of SORT1-positive and HER2-negative or low expression cancers." (PMID 38139459, 2023).
tumor (27 papers, 2020 to 2025). "Our data showed that SORT1 was frequently associated with increased tumor number, advanced TNM stage, and vascular invasion." (PMID 40750784, 2025). "Statistical analysis showed that higher SORT1 expression was associated with tumor multiplicity, higher TNM stage and the presence of vascular invasion." (PMID 40750784, 2025). "The Sort1 expression was associated with the progression of tumor T stage and overall disease progression." (PMID 35847356, 2022). "In addition, the effects of Sort1 on tumor cell behavior and the underlying mechanisms were uncovered through bioinformatics analyses and in vitro experiments." (PMID 35847356, 2022). "Downregulation of SORT1 inhibited proliferation, invasion, migration of tumor cell lines and promoted apoptosis." (PMID 40781926, 2025). "MiR‐146a modulated tumor cell proliferation, migration, invasion, and apoptosis by suppressing SORT1 expression." (PMID 40781926, 2025). "The key findings of this investigation are as follows: Firstly, SORT1 exhibited significant upregulation in tumor tissue derived from NSCLC." (PMID 40781926, 2025). "We observed that SORT1 upregulation increases tumor cell metastasis and invasion by P38/β-catenin/ZEB1 axis." (PMID 40750784, 2025). "Integrative analysis of long-read sequencing data from 8 paired HCC tumor/adjacent tissues and exosomal RNA profiles from EV databases Exocarta identified SORT1 as a top 10 overlapping gene among tumor-upregulated transcripts." (PMID 40750784, 2025). "Elevated SORT1 expression was positively correlated with increased tumor number, advanced TNM stage, and vascular invasion." (PMID 40750784, 2025). "Caudal vein injection models were established to examine the effect of SORT1 on tumor metastasis in vivo." (PMID 40750784, 2025). "The formation of pseudopodium, which improved motility of tumor cell, was increased in SORT1-expressing cells but decreased in SORT1-depleted cells." (PMID 40750784, 2025). "To further validate the functional impact of SORT1-modified exosomes on tumor metastasis, we conducted exosome transfer experiments." (PMID 40750784, 2025). "Multivariate analyses indicated SORT1 as an independent prognostic factor of disease-free survival and tumor recurrence in HCC." (PMID 40750784, 2025). "The present investigation elucidated that SORT1 is significantly overexpressed in NSCLC tumor tissue." (PMID 40781926, 2025). "Molecular validation through qRT-PCR and western blot analysis confirmed the significant downregulation of SORT1 in tumor tissues from the siSORT1 group, corroborating successful knockdown." (PMID 39209807, 2024). "IHS scoring showed that SORT1 expression was increased in tumor tissues, whereas levels remained low in healthy tissues." (PMID 38482021, 2024). "When monitoring tumor progression, the siSORT1 group exhibited a significantly slower growth curve than the NC group, further substantiating the tumor-suppressive role of SORT1 silencing." (PMID 39209807, 2024). "In summary, our data support the fact that SORT1 can be an attractive target for ADC development because of its upregulated expression in tumor cells and high turnover." (PMID 38139459, 2023). "For further experiments, we found that SORT1 is close to mTOR signaling pathway, which lead to the tumor progression." (PMID 36959615, 2023). "The results indicated that CD320, PSMD14, and SORT1 protein levels were higher in tumor tissues than in normal tissues, while the level of NTF3 in the normal tissues was higher than that in the tumor tissues." (PMID 36959615, 2023). "Searches made on the TCGA database indicated that Sort1 was upregulated in HCC tumor tissues compared with paracancerous ones, with similar differences in mRNA levels found after 12 HCC research cohorts from the HCCDB database were analyzed." (PMID 35847356, 2022).
tumor (continued). "Among the various CpG sites linked to SORT1, four (cg02175308, cg23032129, cg16988986, and cg23616212) exhibited significant differences in methylation levels between non-tumor and tumor liver tissues." (PMID 39209807, 2024). "Furthermore, western blot analysis revealed that 17 of the 21 pairs (80.95%) exhibited higher SORT1 expression in HCC tissue samples than in the adjacent non-tumor tissue samples." (PMID 39209807, 2024). "Furthermore, SORT1 methylation status at cg16988986 exhibited significant differences according to the vascular invasion status and tumor stage." (PMID 39209807, 2024). "In addition, we performed RT-qPCR using tumor samples from 12 patients and initially verified that TRAV38-2DV8 and SORT1 expression was remarkably elevated in the low-risk group." (PMID 37511958, 2023). "This suggests that SORT1 is a potentially therapeutic target for tumor therapy." (PMID 38139459, 2023). "To investigate if the internalization profile of SORT1 would provide SORT1-targeted ADCs with a more powerful anti-tumor effect, we compared the cell cytotoxicity between SORT1-targeted ADCs and HER2-targeted ADCs using 8D302-DXd and trastuzumab-DXd, a biosimilar of DS-8201a." (PMID 38139459, 2023). "To further study whether rapid internalization benefited SORT1-targeted ADCs, we compared the tumor suppressive activity of 8D302-DXd and trastuzumab-DXd both in vitro and in vivo." (PMID 38139459, 2023). "SORT1 functions could conjugate cytotoxic agents, like Docetaxel/Doxorubucin, and accurately and specifically inhibit growth of tumor." (PMID 36727070, 2022). "Its diverse functions highlight the significance of SORT1 in maintaining cellular homeostasis and underscore its potential implications in various physiological and pathological conditions, including neurodegenerative disorders, tumours, and metabolic diseases." (PMID 38255751, 2024). "While there is a slightly higher tumor mutational burden in EPAS1-altered tumors (9.9 vs. 4.9 mut/Mb), they are enriched in and associated with genes promoting immune evasion, including ARID5B, SPINT1, AAK1, CLIC3, SORT1, SASH1, and FGFR3, respectively (q < 0.001)." (PMID 36421334, 2022). "In accordance with our previous data, APOE, PMEL, QPCT, and SORT1 were specifically secreted in all metastatic tumor cell lines together with proteins involved in ECM deposition and adhesive proteins supporting the hypothesis of amyloid fibril deposition (Fig EV2F)." (PMID 32749065, 2020). "We found that in both metabolism-related pathways, SLC5A3 + tumor cells exhibit significant communication with CAFs, particularly through the FN1/SDC2, FGF7/FGFR1, NGF/SORT1, and LRPAP1/LRP1 receptor-ligand pairs." (PMID 40652057, 2025). "In light of the clinicopathological data suggesting SORT1 participates in HCC progression, we prioritized the investigation of its role in tumor dissemination." (PMID 40750784, 2025). "SORT1 was negatively correlated with immune and ESTIMATE scores and positively correlated with tumor purity." (PMID 36091132, 2022). "Given the current molecular demonstration that exploiting SORT1 function to internalize TH1902 within these CSC further enables to circumvent their chemoresistance phenotype provides the rationale that such therapy may also impact on the tumor microenvironment of the CSC niche." (PMID 36145658, 2022). "Additionally, SORT1 regulates EGFR internalization from the plasma membrane, thereby constraining proliferative signaling that drives tumor aggressiveness." (PMID 40781926, 2025). "Our findings demonstrated a gradual increase in SORT1 expression as the disease progressed across the four multi-stage datasets and confirmed the SORT1 overexpression in HCC tissues compared to that in non-tumor tissues." (PMID 39209807, 2024).